LRP2 (LDL receptor related protein 2)
Description:
Multiligand endocytic receptor (By similarity). Acts together with CUBN to mediate endocytosis of high-density lipoproteins (By similarity). Mediates receptor-mediated uptake of polybasic drugs such as aprotinin, aminoglycosides and polymyxin B (By similarity). In the kidney, mediates the tubular uptake and clearance of leptin (By similarity). Also mediates transport of leptin across the blood-brain barrier through endocytosis at the choroid plexus epithelium (By similarity). Endocytosis of leptin in neuronal cells is required for hypothalamic leptin signaling and leptin-mediated regulation of feeding and body weight (By similarity). Mediates endocytosis and subsequent lysosomal degradation of CST3 in kidney proximal tubule cells (By similarity). Mediates renal uptake of 25-hydroxyvitamin D3 in complex with the vitamin D3 transporter GC/DBP (By similarity). Mediates renal uptake of metallothionein-bound heavy metals. Together with CUBN, mediates renal reabsorption of myoglobin (By similarity). Mediates renal uptake and subsequent lysosomal degradation of APOM (By similarity). Plays a role in kidney selenium homeostasis by mediating renal endocytosis of selenoprotein SEPP1 (By similarity). Mediates renal uptake of the antiapoptotic protein BIRC5/survivin which may be important for functional integrity of the kidney. Mediates renal uptake of matrix metalloproteinase MMP2 in complex with metalloproteinase inhibitor TIMP1 (By similarity). Mediates endocytosis of Sonic hedgehog protein N-product (ShhN), the active product of SHH (By similarity). Also mediates ShhN transcytosis (By similarity). In the embryonic neuroepithelium, mediates endocytic uptake and degradation of BMP4, is required for correct SHH localization in the ventral neural tube and plays a role in patterning of the ventral telencephalon (By similarity). Required at the onset of neurulation to sequester SHH on the apical surface of neuroepithelial cells of the rostral diencephalon ventral midline and to control PTCH1-dependent uptake and intracellular trafficking of SHH (By similarity). During neurulation, required in neuroepithelial cells for uptake of folate bound to the folate receptor FOLR1 which is necessary for neural tube closure (By similarity). In the adult brain, negatively regulates BMP signaling in the subependymal zone which enables neurogenesis to proceed (By similarity). In astrocytes, mediates endocytosis of ALB which is required for the synthesis of the neurotrophic factor oleic acid (By similarity). Involved in neurite branching (By similarity). During optic nerve development, required for SHH-mediated migration and proliferation of oligodendrocyte precursor cells (By similarity). Mediates endocytic uptake and clearance of SHH in the retinal margin which protects retinal progenitor cells from mitogenic stimuli and keeps them quiescent (By similarity). Plays a role in reproductive organ development by mediating uptake in reproductive tissues of androgen and estrogen bound to the sex hormone binding protein SHBG (By similarity). Mediates endocytosis of angiotensin-2 (By similarity). Also mediates endocytosis of angiotensis 1-7 (By similarity). Binds to the complex composed of beta-amyloid protein 40 and CLU/APOJ and mediates its endocytosis and lysosomal degradation (By similarity). Required for embryonic heart development (By similarity). Required for normal hearing, possibly through interaction with estrogen in the inner ear (By similarity).
Synonyms: LRP-2; gp330; DBS
Tractability: Antibody: UniProt places it where antibodies can reach, with high confidence; its Gene Ontology location is reachable by antibodies, with high confidence; UniProt predicts a signal peptide or a membrane-spanning region. PROTAC: ubiquitination databases record sites on it; its protein half-life has been measured.
Safety:
Unwanted effects reported when the protein is acted on. In parentheses: how it was acted on, where the effect was seen, and who reports it.
hearing loss (source: ClinPGx)
ototoxicity (source: ClinPGx)
Gene: Protein-coding gene on chromosome 2 (169,127,109 to 169,362,534, reverse strand). Ensembl gene ENSG00000081479.
Subcellular location: Apical cell membrane; Endosome lumen; Membrane, coated pit; Cell projection, dendrite; Cell projection, axon
Subcellular location (Human Protein Atlas): Cell Junctions
Pathways (Reactome):
Metabolism: Transport of RCbl within the body; Vitamin D (calciferol) metabolism
Vesicle-mediated transport: Cargo recognition for clathrin-mediated endocytosis; Clathrin-mediated endocytosis
Sensory Perception: Retinoid metabolism and transport
Gene Ontology:
Molecular function: calcium ion binding; cargo receptor activity; protein binding; protein-folding chaperone binding; hormone binding; insulin-like growth factor I binding; low-density lipoprotein particle receptor activity
Biological process: metal ion transport; negative regulation of apoptotic process; phosphatidylinositol 3-kinase/protein kinase B signal transduction; protein transport; receptor-mediated endocytosis; response to leptin; amyloid-beta clearance; cellular response to growth factor stimulus; cobalamin transport; coronary artery morphogenesis; endocytosis; folate import across plasma membrane; lipid metabolic process; male gonad development; negative regulation of BMP signaling pathway; neural tube closure; neuron projection arborization; outflow tract septum morphogenesis; positive regulation of lysosomal protein catabolic process; positive regulation of neurogenesis; positive regulation of oligodendrocyte progenitor proliferation; pulmonary artery morphogenesis; retinoid metabolic process; secondary heart field specification; sensory perception of sound; and 6 more
Cellular component: apical plasma membrane; extracellular exosome; lysosomal membrane; receptor complex; axon; brush border membrane; clathrin-coated endocytic vesicle membrane; dendrite; external side of plasma membrane; lysosome; plasma membrane; apical part of cell; brush border; clathrin-coated pit; endocytic vesicle; endoplasmic reticulum; endosome; endosome lumen; Golgi apparatus; membrane
Genetic constraint (gnomAD): Loss-of-function variants: 161 observed, 521.22 expected, observed/expected ratio (o/e) 0.31, 90% interval 0.27 to 0.35. The upper end of that interval is the gene's LOEUF score, 0.35, which puts it in group 1 of 6, group 1 being the genes least tolerant of losing a copy. Missense variants: 5,040 observed, 6,002.2 expected, observed/expected ratio (o/e) 0.84, 90% interval 0.82 to 0.86. Synonymous variants: 1,953 observed, 2,089.7 expected, observed/expected ratio (o/e) 0.93, 90% interval 0.9 to 0.97.
Gene-disease validity (ClinGen):
ClinGen rates the evidence that LRP2 causes each of these diseases.
congenital heart disease (autosomal recessive): No Known Disease Relationship. A heart disease that is present at birth.
Homologues: Orthologues: chimpanzee LRP2 (99% identical), macaque LRP2 (98% identical), dog LRP2 (79% identical), mouse Lrp2 (77% identical), rat Lrp2 (77% identical), pig LRP2 (71% identical), tropical clawed frog lrp2 (69% identical), zebrafish lrp2a (66% identical), Drosophila melanogaster arr (8% identical). Paralogues in human: LRP1 (36% identical), LRP1B (34% identical), LRP4 (10% identical), LRP6 (9% identical), LRP5 (9% identical), VLDLR (6% identical), LRP8 (6% identical), EGF (6% identical), NID1 (5% identical), NID2 (5% identical), LRP3 (4% identical), and 2 more.
Diseases named in the same sentence as LRP2 in open-access papers:
LRP2 is named in the same sentence as 171 diseases in open-access papers, as found by Europe PMC text mining. Sharing a sentence is not in itself a finding about the gene and the disease. The quoted sentences say what the papers report.
Donnai-Barrow syndrome (21 papers, 2014 to 2026). Donnai-Barrow syndrome (DBS) is a rare, often severe, multiple congenital malformation syndrome with typical facial dysmorphism, ocular findings, hearing loss, agenesis of the corpus callosum, and variable intellectual disability. "Donnai-Barrow Syndrome (DBS) arises from loss-of-function (LoF) variants in the endocytic receptor LRP2/megalin and is characterized by low molecular weight (LMW) proteinuria and developmental abnormalities." (PMID 42024452, 2026). "Donnai-Barrow syndrome (DBS) is a rare autosomal recessive disorder caused by mutation in the low density lipoprotein receptor-related protein 2 gene (LRP2)." (PMID 36777721, 2023). "LRP2 mutations are mainly associated with Donnai-Barrow syndrome and facio-oculo-acoustico-renal syndrome." (PMID 36140739, 2022). "Mutations in LRP2 have been shown to cause Donnai-Barrow syndrome or facio-oculo-acoustico-renal syndrome, a syndrome associated with facial dysmorphism." (PMID 36067312, 2022). "Donnai-Barrow syndrome, a genetic disorder associated to LRP2 (low-density lipoprotein receptor 2/megalin) mutations, is characterized by unexplained neurological symptoms and intellectual deficits." (PMID 33225275, 2020). "LRP2 mutations, as occurring in the Donnai-Barrow/Facio-Oculo-Acoustico-Renal syndrome, result in impaired megalin function." (PMID 32172431, 2020). "Human mutations in Lrp2 are known to cause facio-oculo-acoustico-renal syndrome/Donnai-Barrow syndrome, an autosomal recessive disorder associated with disrupted brain formation, including agenesis of the corpus callosum." (PMID 26949399, 2016). "Mutation of the LRP2 gene causes the severe Donnai-Barrow Syndrome (OMIM # 222448), which is a rare disorder characterized by a set of diverse and inconsistent clinical manifestations." (PMID 24980834, 2014). "Intriguingly, loss of LRP2 activity not only impairs cellular clearance of receptor ligands but also results in breakdown of endocytic structures as shown in the renal proximal tubules of mouse mutants and Donnai-Barrow syndrome patients." (PMID 36764939, 2023). "Another intriguing instance of blended phenotype was described in two DD3 patients first suspected of having DD1 or DD2, but high-throughput sequencing showed mutations in their LRP2 gene, encoding for megalin, and this led to Donnai-Barrow syndrome clinical diagnosis." (PMID 32860533, 2021). "LRP2 is implicated in an autosomal recessive disorder characterized by dimorphisms, ocular anomalies, sensorineural deafness, proteinuria, epilepsy, and intellectual disability: a clinical condition called Donnai-Barrow syndrome (DBS) or facio-oculo-acoustico-renal (FOAR) syndrome." (PMID 37810913, 2023). "We treated C57BL/6J mice featuring the myopic phenotype of Donnai-Barrow syndrome by selective inactivation of Lrp2 knock out (KO) and control mice (CTRL) daily with 1% atropine in the left eye and saline in the right eye, from postnatal days 30-56." (PMID 36882953, 2023). "In line with this concept, obesity is not a feature of the autosomal recessive Donnai-Barrow syndrome that is caused by inactivating bi-allelic mutations in LRP2." (PMID 34066779, 2021). "Furthermore, resemblance of the phenotype of individuals with a STRA6 mutation (Mathew-Woods syndrome) with individuals with an LRP2 mutation (Donnai-Barrow syndrome) is obvious, as is the resemblance of a zebrafish model in which STRA6 function is disrupted with the Lrp2 knockout mouse." (PMID 26822476, 2016). "Mutations in LRP2 have been previously associated with left ventricular non-compaction (LVNC) as well as other congenital heart defects in mouse and in Donnai-Barrow Syndrome in humans." (PMID 33006316, 2020). "Serum selenium levels in patients with DB/FOAR syndrome have not been reported, but it has been shown that LRP2 mediates the reuptake of selenoproteins in the kidney and that LRP2-mutant mice have low selenium serum levels due to the increased urinary excretion of selenoproteins." (PMID 25158045, 2014).
myopia (17 papers, 2014 to 2025). "In conclusion, our study demonstrates that in human eyes with NSHM associated with PS, which is the more severe form of myopia, LRP2 is decreased both in the vitreous and in the RPE." (PMID 40553567, 2025). "In human RPE cells, LRP2 expression is regulated by light, which is the environmental factor that is most associated with myopia." (PMID 40553567, 2025). "It indicates that the patient II:2 in this family carries an autosomal recessive disorder caused by LRP2 variations, and its main clinical features, including high myopia and dysplasia in ears, uterus, and renal, are consistent with that of DBS." (PMID 36777721, 2023). "Our study demonstrates that high myopia caused by Lrp2 insufficiency is prevented by targeting the downstream effector Bmp2." (PMID 35833708, 2022). "Multiple LRP2-deficient animal models exhibit frequent ophthalmic eye enlargement and high myopia, comparable to the phenotypes in DBS patients, involving both homozygous and compound heterozygous states." (PMID 34872573, 2021). "Lrp2 deficient eyes are abnormally enlarged essentially along the anterior-posterior axis, a feature typical of high myopia." (PMID 26107939, 2015). "It implied that when the FZD4 gene is inactivated as a variant, the function of the LRP2 protein will be affected, which may be potentially responsible for high myopia." (PMID 41477247, 2025). "We showed that a low dose of the AAV-Best1-Bmp2 vector can completely prevent the development of high myopia and secondary retinal thinning, which could be a potential early intervention of inherited high myopia caused by Lrp2 genetic defects." (PMID 35833708, 2022). "High myopia is near-universal, and sensorineural hearing loss is very common in patients with variants in genes for type IX or XI collagen, although hearing appears spared in the LRP2 and LOXL3 patients and is variable in GZF1." (PMID 35885918, 2022). "Mutations in LRP2 are associated with Donnai-Barrow syndrome, whose symptoms include buphthalmic eye enlargement and myopia, as well as orbital hypertelorism, diaphragmatic hernia, agenesis of the corpus callosum, facial deformities, hearing loss, and intellectual disabilities." (PMID 31457013, 2019). "Variants in LRP2 are known to cause Donnai–Barrow syndrome, a rare autosomal recessive disorder featuring agenesis of the corpus callosum, sensorineural hearing loss, facial dysmorphism and ocular findings, including myopia and coloboma." (PMID 30568244, 2019). "The premature stop codon of LRP2 in zebrafish induced naturally or artificially, similar to the causal mutations identified for the TE and CE goldfish in this study, also exhibited enlarged eyes, retina degeneration, elevated intraocular pressure, and severe myopia." (PMID 41226661, 2025). "Conditional mutants in which Lrp2 was knocked out only in the RPE also developed myopia and buphthalmos, demonstrating the important role played by LRP2 in the RPE in driving the myopia phenotype." (PMID 40553567, 2025). "Our experiments indicated that exposure to red light seemed to upregulate LRP2 more efficiently than blue or white light, in line with intervention studies in children showing reduced myopia progression by red light therapy." (PMID 40553567, 2025). "LRP2 upregulation by light is in line with epidemiological data showing that light exposure is a robust environmental stimulus in the prevention of myopia." (PMID 40553567, 2025). "As we know, LRP2 variants can cause Donnai–Barrow syndrome (DBS) and high myopia is a major feature of DBS." (PMID 41477247, 2025). "Mutations in human LRP2 lead to Donnai–Barrow and Facio-oculo-acoustico-renal (DB/FOAR) syndrome, characterized by buphthalmia (protuberant eyes), high-grade myopia, etc.." (PMID 41226661, 2025). "The Bugeye zebrafish mutant, possessing a mutation in the low density lipoprotein receptor-related protein 2 (lrp2) was identified and proposed as model for myopia and glaucoma." (PMID 33809186, 2021).
myopia (continued). "In the eye, soluble N-terminal domains of Lrp2 expressed from the RPE lead to eye enlargement and myopia similar to that seen in lrp2 mutant zebrafish." (PMID 31457013, 2019). "In the eye, LRP2 is expressed in the ciliary body and retinal pigment epithelium (RPE), where its absence causes dysregulation of eye size leading to myopia." (PMID 31457013, 2019). "We will combine our transgenic zebrafish line Tg(rpe65a:Gal4 UAS:LDLA1-eGFP), which increases the severity of lrp2 C23X myopia, with the lrp2 S4424N* line to see if the effect is the same." (PMID 31457013, 2019). "Taken together, these data indicate that the presence of exclusively soluble Lrp2 leads to eye enlargement and myopia." (PMID 31457013, 2019). "The association of loss of IRBP function with retinal dystrophy and HM in animal models and humans suggests that retinoic acid could be one of the myopia targets regulated by LRP2." (PMID 40553567, 2025). "LRP2 expressed in RMG cells could also contribute to myopia through the regulation of multiple extracellular protein levels through transport mechanisms, including the metabolism of retinoids." (PMID 40553567, 2025). "Finally, the silencing of LRP2 in human RPE cells regulated the expression of genes involved in myopia development." (PMID 40553567, 2025). "The complex links and the interplay between light, circadian rhythm, corticoids, LRP2, and myopia require further investigations but our results tend to indicate that LRP2 could be a molecular link between light, circadian regulations, and NSHM." (PMID 40553567, 2025). "Furthermore, the Lrp2 knockout phenotype was rescued by RPE-specific overexpression of bone morphogenetic protein 2 (Bmp2), a gene associated with myopia in humans." (PMID 38635876, 2024). "Due to the similarities between lrp2 S4424N*/S4424N* and C23X/C23X homozygous zebrafish eyes, which share phenotypic changes including eye enlargement, myopia, and ciliary epithelial hypoplasia, it is likely that the mechanism that causes these phenotypes is the same." (PMID 31457013, 2019). "Mutations in LRP2 are associated with buphthalmic eye enlargement, myopia and other non-ocular symptoms." (PMID 31457013, 2019). "Interestingly, different aspects of myopia, the most common human eye disease worldwide with increasing incidence, and ocular surface diseases have been established using the zebrafish model, bugeye/lrp2 mutants." (PMID 36982479, 2023). "To further investigate the relationship between myopia, SP, and LRP2 expression in RPE cells, we analyzed the transcriptomic changes induced by partial knockdown of LRP2 in iRPE." (PMID 40553567, 2025). "However, further studies are required to better understand the mechanisms linking LRP2 expression in RPE cells and RMG cells to the development of myopia and PS." (PMID 40553567, 2025). "More recently, the inactivation of the Lrp2 gene in the mouse epiblast via the More-Cre strain was reported to also result in adult-onset myopia but the authors do not provide any evidence that the More-Cre Lrp2 mutants indeed model human myopia." (PMID 26107939, 2015). "In this way, we can assess whether the absence of Lrp2, or the presence of full-length soluble Lrp2 leads to eye enlargement and myopia via the same mechanism." (PMID 31457013, 2019).
myopia (continued). "Human mutations in LRP2, a non-specific co-receptor of SHH also known as megalin, can lead to Donnai–Barrow syndrome, in which large ocular globes can be associated with high myopia and partial colobomas, in contrast to Lrp2-mutant mice presenting micro/anophthalmia." (PMID 30073412, 2019).